NME1 (NME/NM23 nucleoside diphosphate kinase 1)
Diseases named in the same sentence as NME1 in open-access papers (continued):
Sharing a sentence is not in itself a finding about the gene and the disease.
tumor (continued). "NME/NM23 nucleoside diphosphate kinase 1 (Nm23) is a key tumor suppressor involved in metastasis regulation and EMT; its deregulation has been associated with dysfunction in metastasis genes." (PMID 31817513, 2019). "NMEP96S 1-phosphohistidine levels agreed with total NME1 levels and NDPK activity, but were deficient in HPK activity and suppression of tumor cell motility." (PMID 29535799, 2018). "Recent data suggest an essential role for NME1 in the suppression of tumor-virus-induced cell migration and cancer progression." (PMID 30158514, 2018). "Given our reliance on NME1, due to a literature on tumor motility suppression and site-directed mutagenesis, we chose a NME1 HPK substrate, succinic thiokinase, as it fails to histidine autophosphorylate in vitro." (PMID 29535799, 2018). "Drosophila studies have already been crucial in identification of NME1 function in epithelial morphogenesis and our present work shows that it can be a useful model to investigate also this function and its impact on tumour development and progression." (PMID 29203880, 2017). "There were 3, 2, 4, 6, 9 and 1 cohorts reporting the data of NME1 expression and tumor differentiation of the patients with HCC, PC, EC, GC, CRC and GBC, respectively." (PMID 27518571, 2016). "NME/NM23 nucleoside diphosphate kinase 2 (NME2), a ubiquitous enzyme isoform, transforms nucleoside diphosphates into triphosphates, and well known for its homologue NME1 that is a tumor metastatic suppressor." (PMID 25193865, 2014). "The Nm23 gene family (also termed NME) consists of ten related genes in mammals with the NME1 and NME2 isoforms most implicated in tumor progression and sharing about 78% of amino acid identity with the Awd protein." (PMID 24528630, 2014). "Among these identified proteins, NME1 gene, also called Nm23, is the first of 13 identified tumor metastasis suppressor genes." (PMID 22087286, 2011). "The determination of Nme1 expression in primary tumours using our antibody should be an interesting predictive test of the metastasis for clinical investigations." (PMID 8605098, 1996). "In other solid tumors, SIRT7 is highly enriched at promoters of tumor suppressor genes such as nucleoside diphosphate kinase A (NME1), and COP9 signalosome complex subunit 2 (COPS2), as well as the ribosomal protein genes, to inhibit their transcription and promote cell growth and invasion." (PMID 41601922, 2026). "Interestingly, Zbp1−/− tumor cells showed lower expression of H2afz, Nme1, Ran, and Ybx1, but higher expression of Nupr1 compared to WT cells." (PMID 41430036, 2025). "Therefore, we divided the tumor epithelial cells in the single-cell data into NME1-positive (NME1 + Epi) and NME1-negative (NME1-Epi) cell groups to further explore the key mechanisms of nucleotide metabolism." (PMID 39075485, 2024). "Consequently, our data coalesce to portray NME1 as an antagonist of tumor progression, wielding influence over the nucleotide metabolism of tumor cells and thus, indirectly sculpting the tumor microenvironment." (PMID 39075485, 2024). "However, this experiment was performed on plastic support, and it is important to recognize, once again, that tumor microenvironment (TME) is important for NME1 to exert its function as a suppressor or promoter of metastasis." (PMID 39063217, 2024). "NME1 inhibits the proliferation of tumor cells by regulating the MAP kinase pathway." (PMID 39063217, 2024). "Such efforts will not only contribute to a richer understanding of the functional role of NME1 in tumor progression but may also uncover novel therapeutic targets and prognostic markers for a variety of malignancies." (PMID 39075485, 2024). "NME2 has been reported to be an inhibitor of cell motility and invasion, suggesting that it might have a similar function to NME1 during tumor progression as an inhibitor of metastasis." (PMID 37353690, 2023).
tumor (continued). "In addition, mammalian tumor cell lines overexpressing NME1 have increased endocytosis of the EGF receptor and also migrate less than the control cells, and both the increased endocytosis and suppression of migration are blocked by inhibitors of dynamin." (PMID 37353690, 2023). "In PMIS‐miR‐210‐injected tumours, NME1 was widely expressed in tumour sections." (PMID 36116139, 2022). "As the NME1 isoform is present in patients’ serum samples and its level may correlate with stages of tumour progression in several tumour types, there is a need to understand the mechanism(s) by which NME is secreted into the extracellular environment." (PMID 36010906, 2022). "NME1 is a nucleoside diphosphate kinase and a major synthesizer of non-ATP nucleoside triphosphates, perhaps best characterized in its role in inhibiting cell migration and proliferation of tumor cells via inhibition of MAPK signaling." (PMID 36067236, 2022). "Although not completely understood, NME1 has been well-documented to regulate tumor metastasis." (PMID 35259022, 2022). "NME1 was significantly increased in PMIS‐miR‐210 tumour sections compared to PMIS‐EV controls." (PMID 36116139, 2022). "Thus, high levels of miR‐210 expression in SW620 cells reduce XIST transcripts and inhibit NME1 expression to allow for tumour growth." (PMID 36116139, 2022). "This endocytic function of NME1 could contribute to its activity towards the regulation of cell–cell adhesion, cell migration, and invasion during tumor progression." (PMID 36111347, 2022). "Finally, we investigated the consequences of the modulation of NME1/NME2 levels on the ability of tumor cells to proteolytically cleave the surrounding type I collagen fibers." (PMID 34012098, 2021). "Similarly, in BC, the reintroduction of LINC00261 was shown to arrest cell proliferation by protecting NME1 (a known tumor suppressor) mRNA from degradation." (PMID 34022894, 2021). "We also measured the protein levels of ADAM10 in tumor cells genetically modified for NME1 or NME2." (PMID 33918324, 2021). "Reactivation of NME1 expression in tumor cells might thus be a promising avenue to explore for anti-metastatic therapy." (PMID 33918324, 2021). "This function might explain why overexpression of NME1 is observed during tumor proliferation at the early stages of tumorigenesis." (PMID 33918324, 2021). "Mechanistically, LINC00261 may interact with NME1 (a known tumor suppressor) mRNA as protection against degradation, resulting in higher NME1 levels and increased tumor suppression." (PMID 34022894, 2021). "NME1 is a metastasis suppressor, and the cells with a lower level of this protein were found to invade collectively better and express higher levels of genes essential for tumor aggressiveness." (PMID 33807338, 2021). "We assessed the contribution of NME1 to the capacity of tumor cells to remodel and invade through matrix constructs consisting either of Matrigel, with a composition similar to the basement membrane, or type I collagen, the main component of the interstitial tissue." (PMID 34012098, 2021). "Since its activity is directly correlated with the overall outcome in patients, increasing the cytosolic levels of NDPK-A/NME1 in such cancer cells should represent an attractive starting point for novel therapeutic approaches to reduce tumor cell motility and decrease metastasis." (PMID 32384736, 2020). "NME1 is overexpressed in the primary tumor in the early tumorigenesis but lost during metastasis." (PMID 32823988, 2020). "The role of NME1 as a suppressor of metastasis has also been suggested by several studies where the depletion of NME1 enhances tumor metastases in xenograft models, whereas NME1 expression is associated with regulation of genes correlated with adult cancer metastases." (PMID 32392889, 2020). "The NME1 HPK pathway has been correlated with tumor motility suppression." (PMID 29535799, 2018).
tumor (continued). "By maintaining the homeostasis of cellular nucleoside di- and triphosphate composition, NME1 is involved in a variety of biological events such as tumor metastasis, cell proliferation, differentiation, motility, transcriptional regulation, development, senescence, and apoptosis." (PMID 29467924, 2018). "While general levels of NME correlated with its 1-phosphohistidine form in two cell line model systems, two exceptions were noted: Tumor cells actively migrating in scratch assays, even if expressing high levels of NME1, were low in its 1-phosphohistidine form." (PMID 29535799, 2018). "NME1 (granzyme A-activated DNase, metastasis inhibition factor nm23), the first metastasis suppressor gene identified, is a tumor suppressor that negatively regulates cell migration/motility and inhibits the cell cycle through downregulation of cyclin B, an effect inhibited by cAMP." (PMID 29507682, 2018). "NME1 (also known as NM23-H1 and NDPK-A), the first metastasis suppressor protein of the ten members of NM23 family (NM23 stands for non-metastatic clone 23), has been found associated with the development and progression of various neoplasms." (PMID 27518571, 2016). "Fortunately, we discovered that elevated NME1 expression might be related to well tumor differentiation and N status." (PMID 27518571, 2016). "The known tumor gene NME1 (non-metastatic 1; encoding the NM23A protein, a nucleoside diphosphate kinase) is among the most frequently up-regulated genes in this region." (PMID 16982006, 2006). "Moreover, a low level of histidine phosphatase LHPP was correlated with high PRAME expression in PRAME-positive UM tumor cells, but opposite phenomenon as high level of histidine kinase (NME1 and NME2), which indicates that low LHPP expression forebodes a risk of easier metastasis." (PMID 40988976, 2025). "The authors postulated that pAsp319 could be involved in the tumour-suppressive effects of NME1 observed in cultured breast cancer MDA-MB-435 cells, given the correlation of the phosphate transfer activity with inhibition of cell motility, but this was not definitively ascertained." (PMID 41124372, 2025). "Furthermore, NME1 was found to have a tumor-suppressive role in mice with either WT or R58E NME1." (PMID 39063217, 2024). "Indeed, loss of NME2, unlike NME1, does not impair the invasive capacity of tumor cells or the transition from in situ to invasive breast carcinoma in the intraductal xenograft model." (PMID 37353690, 2023). "In addition to its known function as a nucleotide-diphosphate kinase that converts nucleoside diphosphates to nucleoside triphosphates at the expense of adenosine triphosphate (ATP), NME1 is involved in several pathological processes such as motility and metastasis of tumor cells." (PMID 32977620, 2020). "Similarly, NME1 binds to gelsolin and inactivates its effects on actin to suppress tumor motility." (PMID 32823988, 2020). "The DNA repair pathway plays a role in tumor dissemination, and molecules such as poly (ADP-ribose) polymerase 1 (PARP1), NME/NM23 nucleoside diphosphate kinase 1 (NME1) and proliferating cell nuclear antigen (PCNA) are highly expressed in metastatic lesions." (PMID 39780291, 2025). "The gene nm23-H1 (NME1) is a candidate metastasis suppressor and is involved in the control of tumor diffusion in EOCs." (PMID 41376748, 2025). "An increasing number of studies implicate NME1 and NME2 in cancer, but depending on the cancer context, they can either be protumorigenic or tumor suppressive." (PMID 39063217, 2024).
tumor (continued). "Laboratory experiments have revealed that NME1 can inhibit the proliferation and invasion of CRC tumor cells." (PMID 39075485, 2024). "Accordingly, NME1 and NME2 are overexpressed early in the primary tumor and only NME1 expression is reduced or repressed at later stages in colorectal and hepatic tumors that have undergone metastasis." (PMID 37353690, 2023). "RNA sequencing of SW620 cells and tumours transduced with PMIS‐EV or PMIS‐miR‐210 revealed an increase in NME1 transcripts in the PMIS‐miR‐210 cells and tumours compared to controls." (PMID 36116139, 2022). "NME1 was increased in both SW620 cells and tumours when miR‐210 was inhibited and confirmed by qPCR and Western blot analyses." (PMID 36116139, 2022). "We profiled PMIS‐miR‐210 transduced and untreated CRC cells and tumours for gene expression changes and focused on two genes XIST and NME1 that were significantly affected by miR‐210 inhibition." (PMID 36116139, 2022). "Because XIST expression was significantly increased in SW620 cells and tumours expressing PMIS‐miR‐210, we asked if XIST also contributed to epigenetic regulation of NME1." (PMID 36116139, 2022). "NME1 and NME2 have been reported to be over-expressed in CRC tumor tissues compared with normal tissues in a significant proportion of the patients." (PMID 34113558, 2021). "The catalytic activity of NME2 is similar to that of NME1 (NME1: 748 U/mg and NME2: 609 U/mg; unpublished data) and this isoform has also been observed to be overexpressed during tumor proliferation." (PMID 33918324, 2021). "The higher rate of face tumours in HPN2 versus HP or HPN1 mice suggests Nme2 deficiency imparts a more external and UV-exposed location of melanocytes in face skin, or that Nme2 might play a more dominant role than Nme1 in the repair of UV-induced DNA damage in those melanocytes." (PMID 33024267, 2021). "Nm23-H1, also known as NDPK-A or NME1, has been identified tumor suppressor gene inhibiting metastasis in various cancers." (PMID 34400947, 2021). "There is a growing appreciation for the notion that metastasis-regulating genes, such as KISS1, BRMS1, NME1 or SMAD4, exert their effects at both the tumor and TME level." (PMID 29050279, 2017). "Proteins important for tumor cell survival (SND1), proteins known to be expressed by MM cells (PPA1, CCT3, NME1, SPAG9), and a marker for bone resorption (DPYD) were detected at higher levels in the NBM coculture supernatants." (PMID 26545722, 2015). "NME1, which was overexpressed in OSCC, plays an important role in cell movement, invasiveness, disease stage and tumour genesis." (PMID 26269723, 2014). "These conflicting reports of both positive and negative correlation of NME1 expression with metastasis depending on the tumor type, are highly suggestive of context-specific mechanisms." (PMID 37353690, 2023). "We hypothesise that that NME1 and NME2 function as NDPKs at early stages of tumorigenesis, providing nucleoside triphosphates to sustain the high proliferation of tumor cells." (PMID 37353690, 2023). "Thus, we performed RNAscope staining and detected a coexpression pattern of FABP5, NME1, and MKI67 across the tumor tissues." (PMID 37402315, 2023). "It is interesting to note that this analysis did not indicate any predicted activation relationships; rather, relationships related to inhibition (for seven proteins: LMNA, NME1, PKM, S100A4, SERPINA1, VIM, and AHCY) were indicated for both increased and decreased proteins in the tumor." (PMID 35512017, 2022). "NME1 was identified as a gene upregulated in both PMIS‐miR‐210 cells and tumours." (PMID 36116139, 2022).
tumor (continued). "NME1 is a metastasis suppressor protein with the ability to suppress the metastatic phenotype of cancer cells without affecting primary tumour growth." (PMID 36116139, 2022). "The NDPK protein family is encoded by NME genes, initially called NM23 (non-metastatic 23) after the first identified member NM23-H1/NME1, which is associated with the tumor metastatic process." (PMID 35170678, 2022). "Finally, we investigate the role of nucleoside diphosphate kinase A (NME1), a gene we previously found upregulated during metastatic seeding of PDX tumor cells." (PMID 34741115, 2021). "NME1 is a metastasis suppressor, a class of proteins which inhibits metastatic spread of cancer cells without impact on growth of the primary tumor." (PMID 32029850, 2020). "While NME1 NDPK activity has been shown to contribute to dynamin function and endothelial cell contractility, the relative role of NME1 histidine kinase activity in the process of tumor cell metastasis remains to be determined." (PMID 32392889, 2020). "This interaction between NME1 and MIF may result in a negative regulatory effect of NME1 on tumor metastasis." (PMID 30158514, 2018). "Enforced expression of NME1 was shown to suppress metastatic potential in a variety of cell lines, and with the notable absence of impacts on proliferative or tumor-forming capacity." (PMID 28788083, 2017). "Unlike its homologue NME1 as a tumor suppressor, notably, it is regarded as an activator of c-Myc expression in human tumor cells." (PMID 25193865, 2014). "Additionally, MDK (3.99), NME1 (4.82), and PA2G4 (4.21) showed increased expression in the tumor tissues from the patients with recurrent HCC." (PMID 24377043, 2013). "Therefore, it is important to keep in mind that the role of NME1 could depend on the model of study as well as the tumor microenvironment (TME), which seems to play an important role in whether NME1 suppresses or promotes tumor metastasis." (PMID 39063217, 2024). "NME1 WT or R58E overexpression did not significantly affect primary tumor growth, as expected." (PMID 35259022, 2022). "Finally, NME1 promoted dynamin-mediated endocytosis of the transmembrane metalloproteinase MT1-MMP, known as a key player in tumor invasion, resulting in a strong reduction of surface MT1-MMP levels and a concomitant reduction of extracellular matrix degradation and invasion." (PMID 36111347, 2022). "We find that NME1 overexpression promotes metastasis of orthotopically transplanted, cultured PDX cells, providing proof-of-principal for the value of this culture-transplant system for facilitating functional analyses of new genes of interest in patient tumor cells." (PMID 34741115, 2021). "In In Vitro experiments performed in a variety of tumor cells, it was shown that NDPK-A/NME1 re-expression reduced the migration in Boyden chamber as well as wound healing assays stimulated with multiple attractants, which suggest a central role in the regulation of tumor cell motility." (PMID 32384736, 2020). "By contrast, tumor-associated CD4+ T cells projected mostly onto resting blood and tissue T cells, while CD4+ T cell activation states and associated markers (NME1, IFIT3) were largely absent." (PMID 31624246, 2019). "Suppression of NME1, but not that of NME2, accelerated the invasive switch of MCF10DCIS.com tumor xenografts in the intraductal injection model." (PMID 34012098, 2021). "Apart from these metastasis-promoting genes, there is a well-distinguished class of metastasis “suppressor” genes that represses tumor cell dissemination without any effect on primary tumor growth, including KAI-1, BRSM1, and NME1." (PMID 27351280, 2016). "Apart from these metastasis-promoting genes, there is a well-distinguished class of metastasis “suppressor” genes that represses tumour cell dissemination without any effect on primary tumour growth, including KAI-1, BRSM1, and NME1." (PMID 22567347, 2011).